ZMYND10 (zinc finger MYND-type containing 10)
Description:
Plays a role in axonemal structure organization and motility. Involved in axonemal pre-assembly of inner and outer dynein arms (IDA and ODA, respectively) for proper axoneme building for cilia motility (By similarity). May act by indirectly regulating transcription of dynein proteins (By similarity).
Synonyms: BLU; CILD22; DNAAF7; FLU
Tractability: Antibody: UniProt places it where antibodies can reach, with medium confidence; its Gene Ontology location is reachable by antibodies, with medium confidence; the Human Protein Atlas places it where antibodies can reach. PROTAC: ubiquitination databases record sites on it.
Gene: Protein-coding gene on chromosome 3 (50,341,110 to 50,345,732, reverse strand). Ensembl gene ENSG00000004838.
Subcellular location: Cytoplasm; Cytoplasm, cytoskeleton, microtubule organizing center, centrosome, centriolar satellite; Apical cell membrane; Dynein axonemal particle
Subcellular location (Human Protein Atlas): Basal body; Plasma membrane; Cytosol
Gene Ontology:
Molecular function: protein binding; molecular adaptor activity; protein folding chaperone
Biological process: inner dynein arm assembly; motile cilium assembly; outer dynein arm assembly; positive regulation of motile cilium assembly; protein folding
Cellular component: cytoplasm; apical plasma membrane; centriolar satellite; dynein axonemal particle
Genetic constraint (gnomAD): Loss-of-function variants: 52 observed, 65 expected, observed/expected ratio (o/e) 0.8, 90% interval 0.64 to 1.01. The upper end of that interval is the gene's LOEUF score, 1.01, which puts it in group 4 of 6, group 1 being the genes least tolerant of losing a copy. Missense variants: 438 observed, 563.92 expected, observed/expected ratio (o/e) 0.78, 90% interval 0.72 to 0.84. Synonymous variants: 197 observed, 227.18 expected, observed/expected ratio (o/e) 0.87, 90% interval 0.77 to 0.98.
Gene-disease validity (ClinGen):
ClinGen rates the evidence that ZMYND10 causes each of these diseases.
primary ciliary dyskinesia 22 (autosomal recessive): Definitive.
Homologues: Orthologues: chimpanzee ZMYND10 (99% identical), macaque ZMYND10 (98% identical), pig ZMYND10 (91% identical), dog ZMYND10 (90% identical), rat Zmynd10 (89% identical), mouse Zmynd10 (89% identical), guinea pig ZMYND10 (85% identical), tropical clawed frog zmynd10 (57% identical), zebrafish zmynd10 (55% identical), Drosophila melanogaster Zmynd10 (33% identical). Paralogues in human: MSS51 (14% identical), ZMYND19 (11% identical).
Diseases named in the same sentence as ZMYND10 in open-access papers:
ZMYND10 is named in the same sentence as 25 diseases in open-access papers, as found by Europe PMC text mining. Sharing a sentence is not in itself a finding about the gene and the disease. The quoted sentences say what the papers report.
primary ciliary dyskinesia (12 papers, 2015 to 2025). A rare, genetically heterogeneous, primarily respiratory disorder characterized by chronic upper and lower respiratory tract disease. "Several genes (ARMC4, SP2, LRRC46, RSPH9, and ZMYND10) assigned to associations are involved in primary ciliary dyskinesia (PCD), an autosomal recessive inherited disease." (PMID 35052452, 2022). "The Zmynd10 protein functions assembling the arms of axonemal dynein and mutations on its coding gene cause ciliopathy primary ciliary dyskinesia (PCD) in humans." (PMID 35155449, 2021). "Zinc finger MYND-type-containing 10 (ZMYND10), a cytoplasmic protein expressed in ciliated cells, causes primary ciliary dyskinesia (PCD) when mutated; however, its function is poorly understood." (PMID 29601588, 2018). "It has been reported that individuals with biallelic truncating variants in ZMYND10 were found to have primary ciliary dyskinesia with or without laterality defects, and lacking both inner and outer dynein arms observed by TEM evaluation." (PMID 29402277, 2018). "A study of Polish patients with primary ciliary dyskinesia (PCD) has resulted in the identification of two recurrent alleles, DNAI1 c.1612G>A (p.Ala538Thr) and ZMYND10 c.367delC (p.His123Thrfs*16)." (PMID 39273284, 2024). "In primary ciliary dyskinesia (PCD [MIM 244400]) affected families, biallelic variants in ZMYND10 (MIM 607070; GenBank Accession Number NM_015896.2) were found to be shared by affected individuals from each of families with biallelic variants of interest." (PMID 36520265, 2022). "Among 32 genes in which defects lead to primary ciliary dyskinesia, six (Dnaic2, Ccdc40, Armc4, Ccdc164/DRC1, Rsph9, Ccdc11) are strongly downregulated in Rfx2-/- testes at both time points, and three others only at P30 (Ccdc65, Zmynd10, Ccno)." (PMID 26162102, 2015).
breast carcinoma (6 papers, 2015 to 2023). "ZMYND10 was dramatically reduced in multiple breast cancer cell lines and tissues, which was associated with promoter hypermethylation." (PMID 31801619, 2019). "Ectopic expression of ZMYND10 in breast cancer cells induces apoptosis and inhibits cell growth, migration, and invasion in vitro and in vivo." (PMID 37353691, 2023). "In breast cancer, ZMYND10 via increasing expression of miR-145 and downregulation of NEDD9 suppressed proliferation, migration, and invasion of cells." (PMID 34479583, 2021). "MSP was used to examine ZMYND10 methylation in 138 primary breast cancer tissue, 40 breast cancer-adjacent tissue, 46 breast fringe, and 8 normal breast tissue samples." (PMID 31801619, 2019). "Ectopic expression of ZMYND10 in silenced breast cancer cells induced cell apoptosis while suppressed cell growth, cell migration and invasion in vitro, and xenograft tumor growth in vivo." (PMID 31801619, 2019). "qPCR assay was performed to confirm the inhibitory effect of ZMYND10 on NEDD9 expression in breast cancer cells." (PMID 31801619, 2019). "In a rescue experiment, overexpression of NEDD9 partially attenuated the ability of ZMYND10 in inhibiting migration and invasion of breast cancer cells." (PMID 31801619, 2019). "ZMYND10 mRNA levels were much lower in breast cancer tissues than that in normal breast tissue in basal-like (ER-/PR-/HER2-) tumors (14/16)." (PMID 31801619, 2019). "Altogether, the results suggested that ZMYND10 is able to suppress migration and invasion of breast cancer cells by inhibiting NEDD9 expression." (PMID 31801619, 2019). "Results from this study show that ZMYND10 suppresses breast cancer tumorigenicity by inhibiting the miR145-5p/NEDD9 signaling pathway." (PMID 31801619, 2019). "ZMYND10 was significantly reduced in multiple breast cancer cell lines (7/10), but broadly expressed in all normal breast tissue." (PMID 31801619, 2019). "Silencing of ZMYND10 by promoter methylation in breast cancer cell lines as well as primary tumors suggested ZMYND10 as a functional tumor suppressor in breast cancer." (PMID 31801619, 2019). "MSP analysis showed that ZMYND10 CpG island was methylated in 80% (8/10) of breast cancer cell lines." (PMID 31801619, 2019). "ZMYND10 suppresses breast cancer oncogenicity by inhibiting the miR145-5p/NEDD9 signaling pathway." (PMID 36158689, 2022). "Here, we investigated the role and mechanism of ZMYND10 in breast cancer inhibition." (PMID 31801619, 2019). "Although it has been suggested that ZMYND10 downregulation or silencing is closely correlated to its promoter CpG methylation, its biological functions and molecular mechanisms in breast cancer remain unknown." (PMID 31801619, 2019). "Thus, a possible link between promoter methylation and downregulation of ZMYND10 expression in breast cancer was investigated." (PMID 31801619, 2019). "The qPCR assay data showed that miR-145-5p inhibitor was added to ZMYND10-expressing breast cancer cells could reduce the expression of miR145-5p and increased the expression of NEDD9." (PMID 31801619, 2019). "Together, these data demonstrated a reduction in ZMYND10 expression in breast cancer, which may be an indicator of breast cancer prognosis." (PMID 31801619, 2019). "To investigate whether ZMYND10 is downregulated in breast cancer, we first used immunohistochemistry assay to examine its expression in tumor-adjacent (n = 16) and tumor tissues (n = 27)." (PMID 31801619, 2019). "In addition, there is evidence that miRNA-145 could regulate tumor suppressor ZMYND10, because it can inhibit the miRNA-145 signaling pathway, thereby inhibiting the tumorigenicity of breast cancer." (PMID 37047783, 2023). "The results clearly showed that ZMYND10 could inhibit the PI3K/AKT pathway in breast cancer cells." (PMID 31801619, 2019). "However, the mechanism by which ZMYND10 inhibits breast cancer remains unclear." (PMID 31801619, 2019).
breast carcinoma (continued). "Because ZMYND10 was reported to inhibit PI3K/AKT and NEDD9 participated in AKTactivation in certain circumstances, we examined if ZMYND10 affects this pathway in breast cancer." (PMID 31801619, 2019). "In this study, we found that ZMYND10 suppresses breast cancer tumorigenicity through upregulating miR-145-5p to inhibit the expression of oncogene NEDD9, which results in suppression of cell invasion and migration and breast cancer progression." (PMID 31801619, 2019). "ZMYND10 promoter methylation was detected in 101 of 138 (73%) breast cancer tissue samples, but not in normal breast tissues (0/8)." (PMID 31801619, 2019).
nasopharyngeal carcinoma (5 papers, 2012 to 2022). A carcinoma arising from the nasopharyngeal epithelium. "Over expression of ZMYND10 can reduce the migration, invasion and angiogenesis of nasopharyngeal carcinoma cells." (PMID 32271791, 2020). "(2020) reported top three hub genes of PPI network of FANCI, POSTN, IFIH1, ZMYND10, PACRG and POU2AF1 for nasopharyngeal carcinoma biomarkers using STRING database PPI network construction with MCODE for module analysis." (PMID 36299526, 2022).
lung carcinoma (3 papers, 2015 to 2022). "ZMYND10 (Zinc finger, MYND-type containing 10) has recently been identified as a candidate tumor suppressor gene due to the occurrence of mis-sense mutations and loss of its expression in lung cancer." (PMID 25657825, 2015). "Specifically, in lung cancer the ZMYND10 expression was elevated and its promoter exhibited reduced methylation compared to normal tissue samples." (PMID 28634396, 2017). "Among members of the ZMYND family, programmed cell death 2 (PDCD2)/ZMYND7, ubiquitin specific protease 19(USP19)/ZMYND9, and beta catenin in lung cancer (BLU)/ZMYND10 only contain MYND motif in their respective carboxylterminus, with length between 30 and 40 amino acid residues." (PMID 36520265, 2022).
endometritis (2 papers, 2021 to 2022). An acute or chronic, usually bacterial infectious process affecting the endometrium. "Moreover, co-expression and interactions between lncRNAs and the CCDC40 and ZMYND10 are involved in bovine endometritis." (PMID 35887003, 2022).
esophageal squamous cell carcinoma (2 papers, 2020 to 2022). Esophageal squamous cell carcinoma (ESCC) is a type of esophageal carcinoma (EC) that can affect any part of the esophagus, but is usually located in the upper or middle third. "The expression of ZMYND10 has been found to absence in 20% of hepatoma cases, and a number of esophageal squamous cell carcinoma (ESCC)." (PMID 36520265, 2022). "Zinc finger MYND domain-containing protein 10 (ZMYND10), also known as BLU, is significantly down-regulated in several primary tumours such as neuroblastoma, esophageal squamous cell carcinoma and also malignancies in lung, breast, kidney." (PMID 32271791, 2020).
breast tumor (1 paper, 2019). "ZMYND10 expression was significantly lower in breast tumor samples(22/27) than in breast tumor-adjacent tissues." (PMID 31801619, 2019). "Bisulfite genomic sequencing was then used to measure the methylation of ZMYND10 CpG in MB468 and MDA-MB231 cells treated with Aza and TSA and two-paired normal breast and breast tumor tissue samples, which verified the MSP results." (PMID 31801619, 2019). "Furthermore, the ZMYND10 mRNA expression level was detected by qPCR in paired breast tumor and adjacent non-tumor tissues with different ER/PR/HER2 statuses." (PMID 31801619, 2019).
hepatoblastoma (1 paper, 2022). Hepatoblastoma (HB) is a malignant hepatic tumor and is the most common pediatric liver cancer. "We have recently described that ZMYND10 is associated with SIN3A when re-expressed in a hepatoblastoma line HepG2." (PMID 36520265, 2022).
Hydrocephalus (1 paper, 2018). Hydrocephalus is an active distension of the ventricular system of the brain resulting from inadequate passage of CSF from its point of production within the cerebral ventricles to its point of absorption into the systemic circulation. "Therefore, in this study, we examined the roles of ZMYND10 using Zmynd10–/–mice exhibiting typical PCD phenotypes, including hydrocephalus and laterality defects." (PMID 29601588, 2018).
Infertility (1 paper, 2025). "Among women with known genetic results, those with infertility had DNAH5, DNAAF3, ZMYND10, CCDC40, RSPH9 and HYDIN mutations." (PMID 40142748, 2025).
male infertility (1 paper, 2020). The inability of the male to effect fertilization of an ovum after a specified period of unprotected intercourse. "Male infertility has also been detected in PCD patients with mutations in axonemal dynein assembly factors LRRC6 (leucine-rich repeat containing 6), ZMYND10 (zinc finger MYND-type containing 10) and cilia and flagella-associated protein 300 (CFAP300)." (PMID 31781811, 2020).
ovarian carcinoma (1 paper, 2022). A malignant neoplasm originating from the surface ovarian epithelium. "In addition, ZMYND10 can upregulate BAX expression, which facilitates the pro-apoptotic pathway, thereby promoting paclitaxel-induced apoptosis in ovarian cancer cells." (PMID 36158689, 2022).
tumor (17 papers, 2008 to 2023). "We have recently reported that another member of ZMYND family, ZMYND10 encoded by tumor suppressor BLU on chromosomal 3p region binds Sin 3A and this may contribute to its tumor suppression through modulation of proliferation and apoptosis related gene expression." (PMID 36520265, 2022). "The implication of such binding in the genesis of the liver cancers remains to be characterized, the data, however, supports that BLU/ZMYND10 contribute to suppressing tumor formation through transcription repression." (PMID 36520265, 2022). "Study in human cancer cells suggests that ZMYND10 behaves as a signaling molecule, and, combined with the findings of its downregulation in tumor tissues and cancer cells." (PMID 36520265, 2022). "In recent decades, documented studies have confirmed that ZMYND10 is a tumor suppressor that can induce apoptosis, arrest cell cycle, and inhibit proliferation and angiogenesis in different tumors." (PMID 31801619, 2019). "Here, we confirmed that RASSF1A is frequently hypermethylated in 69 NSCLC; conversely the upstream gene ZMYND10 is relatively hypomethylated in these tumor samples compared to normal lung tissues." (PMID 28634396, 2017). "This region contains among others RASSF1A and ZMYND10; two candidate tumor suppressor genes that are epigenetically silenced in a proportion of NB tumors." (PMID 18664255, 2008). "In addition, Zinc finger MYND domain-containing protein 10 (ZMYND10) is a tumor suppressor gene in the 3p21.3 region." (PMID 37353691, 2023). "While global screening of how multiple epigenetic codes act on ZMYND10 mediated tumor suppression remains to be done, reversing of H3K9 demethylation by ZMYND10 leading to repressing expression of cell cycle regulator has been suggested, as supported in part by some published work." (PMID 36520265, 2022). "For example, ZMYND10 (zinc finger, MYND type containing 10) has been labeled as a gene involved possibly in tumor suppression, making it capable of cell cycle arrest, proliferation and angiogenesis inhibition, as well as apoptosis induction in multiple tumor types." (PMID 34721975, 2021). "Recent studies suggested that ZMYND10 is a potential tumor suppressor gene in multiple tumor types." (PMID 31801619, 2019). "Functional evidence suggests that the ZMYND10 gene inhibits tumor growth in animal experiments." (PMID 31850229, 2019). "A wound-healing assay was performed to investigate whether ZMYND10 suppresses tumor cell migration." (PMID 31801619, 2019). "The expression of ZMYND10 is down-regulated in cancers and may be a tumor suppressor." (PMID 23604077, 2013). "Two tumor suppressors involved in epigenetic regulation were progressively lost in LGSC and its corresponding metastasis (ZMYND10, OSCP1/NOR1), as was Anterior Gradient Protein 2/3 (AGR2/3) previously implicated in the progression of SBT to LGSC16." (PMID 38014221, 2023). "Among them, 10 genes have been reported in HCC, and ZMYND10, SYK, DAB2IP, and DLEC1 have been reported to be tumor-suppressor genes in HCC." (PMID 21625442, 2011). "To further study the role of differentially expressed lncRNAs in tumor, we discovered through GO enrichment analysis that most differentially expressed lncRNAs were related to microtubule movement, including DYNLRB2, CFAP91, and ZMYND10." (PMID 37224123, 2023).
cancer (13 papers, 2008 to 2023). A tumor composed of atypical neoplastic, often pleomorphic cells that invade other tissues. "ZMYND10 is also one of several loss of function genes associated with several types of cancers, but its role is unclear." (PMID 23604077, 2013). "Importantly, many of the MYND-containing proteins are associated with cancer and other diseases (e.g. ZMYND10, ZMYND11/BS69, ETO (eight-twenty-one)/MTG (myeloid translocation gene) family members, DEAF1, and Suppressin." (PMID 23408894, 2013). "Other anomaly like copy number variation (CNV) of BS69/ZMYND11 and promoter hyper methylation of BLU/ZMYND10 has been noted in malignancies." (PMID 36520265, 2022). "We have observed that similarly with RASSF1A, BLU/ZMYND10 interferes the activity of mutant Ras to prevent cancer cell proliferation by inhibiting MAPK/ERK signaling." (PMID 36520265, 2022). "It will be interesting to analyze if suppression of ZMYND10 leads to reactivation of the RASSF1A in cancer cells." (PMID 28634396, 2017). "Recently a report examining the methylation of CDH13, CDKN2A/p16, FHIT, RARB, RASSF1A and ZMYND10 (BLU) in which methylation of any 2 loci in plasma was considered cancer positive showed 73% sensitivity and 82% specificity." (PMID 18947422, 2008). "The 3p.21.31 region may harbor candidate tumor suppressor genes due to the frequent copy number loss in various cancer types, including HYAL2, TUSC2, RASSF1, ZMYND10, NPRL2, CYB561D2, TMEM115. and CACNA2D2." (PMID 31323949, 2019). "Interestingly only 6 genes including CCDC19, MMP1, SLC family, TEKT2, WDR family and ZMYND10 had been reported relevant to cancer survival in a separate study (where a total of 88 genes were reported,)." (PMID 25551281, 2014). "We and others previously discovered that several 3p22-21.3 genes including RASSF1A, BLU, DLEC1, ZMYND10 and PLCD1 were frequently methylated in various cancers." (PMID 36849889, 2023). "Further, AIWrap identified six new genes (VCX3A, CALHM5, ZMYND10, FOXE1, PLAT, FADD) which could be related to smoking in cancer patients, thus providing an opportunity for identifying previously unknown biological functions." (PMID 37853338, 2023). "For this reason, despite their proximity, RASSF1A has often been found down-regulated in cancer as opposed to ZMYND10." (PMID 31323949, 2019). "Furthermore, cancers with high expression of the FREM1 gene were sensitive to XAV939 and dasatinib and resistant to SB590885 and gemcitabine, and cancers with high expression of ZMYND10 were resistant to XAV939, gemcitabine, and SB590885." (PMID 36158689, 2022).
ZMYND10 also shares sentences with these, for which no sentence is quoted: neuroblastoma (2 papers); scoliosis (2); cone-rod dystrophy (1); gastric cancer (1); glioblastoma (1); idiopathic scoliosis (1); infection (1); Kartagener Syndrome (1); non-small cell lung carcinoma (1); Situs inversus totalis (1); spondylometaphyseal dysplasia (1).